PIEZO1 (piezo type mechanosensitive ion channel component 1 (Er blood group))
Diseases named in the same sentence as PIEZO1 in open-access papers (continued):
Sharing a sentence is not in itself a finding about the gene and the disease.
tumor (continued). "The positive correlation with higher tumor grade further supports the potential role of PIEZO1 in promoting tumor growth and advancement." (PMID 40724850, 2025). "Piezo1 plays a significant role in various tumor cell types, although its functions differ depending on the cancer type." (PMID 40821847, 2025). "In oncology, PIEZO1 promotes tumor angiogenesis and immune evasion through VEGF and MMP upregulation." (PMID 40863236, 2025). "Elevated PIEZO1 correlates with advanced tumor stages (e.g., LIHC, PAAD) and metastatic status (SARC), indicating its association with aggressive phenotypes." (PMID 40977743, 2025). "Among the 111 tumor samples analyzed, low PIEZO1 expression was identified in 59 cases (53.15%), while high expression was observed in 52 cases (46.85%)." (PMID 40724850, 2025). "As a central hub for mechanical signal transduction in the TME, Piezo1 integrates mechanical and biochemical signals to regulate several key aspects of tumor progression." (PMID 40821847, 2025). "PIEZO1 is abnormally overexpressed in multiple tumor types and regulates stemness characteristics to influence tumor progression." (PMID 41533929, 2025). "The stretch‐induced tumor cell apoptosis (mechanoptosis) relied upon the mechanosensitive Piezo1 channels that catalyzed calcium entry, and we postulated that ultrasound‐induced apoptosis involved a similar mechanism." (PMID 40060768, 2025). "In summary, Piezo1 plays multifaceted roles in the tumor immune microenvironment, promoting immune evasion by modulating immune-cell functions." (PMID 40821847, 2025). "The in vivo analysis also strengthened the findings on the importance of Piezo1 in tumor progression." (PMID 40361464, 2025). "In the direct interaction between T cells and tumor cells, Piezo1 primarily modulates cytotoxicity by regulating immune-synapse structural stability and T-cell traction." (PMID 40821847, 2025). "Mechanosensitive ion channels, like PIEZO1, further respond to tumor mechanical cues, regulating angiogenesis and cell migration." (PMID 40361464, 2025). "Overall, PIEZO1 expression was significantly reduced in ccRCC tissues compared to adjacent non-tumor kidney tissues (p < 0.0001)." (PMID 40724850, 2025). "The RNA-Seq data from the TCGA showed that the PIEZO1 expression was significantly increased in ccRCC tumor tissues compared to the matched adjacent normal tissue (p < 0.0001)." (PMID 40724850, 2025). "Both HCC and glioblastoma models have validated the efficacy of Piezo1 blockade in promoting antitumor immunity and attenuating tumor progression." (PMID 39799341, 2025). "As an inhibitor of mechanically sensitive ion channels, GsMTx4 enhances the therapeutic efficacy of tumor treatment by specifically targeting PIEZO1." (PMID 40535121, 2025). "Overall, higher Piezo1 expression correlated with lower tumor burden in vivo, and decreased for the FUS condition." (PMID 39976192, 2025). "It is therefore plausible that mechanical stimuli within the tumour microenvironment, such as matrix stifness, induce local plasma membrane deformation, thereby activating Piezo1 and triggering Ca2+ influx and downstream KCa activation." (PMID 40838979, 2025). "The percentage of proliferatively active GBM stem cells and the total number of cells increased with increasing stiffness, while Piezo1 knockdown eliminated this stiffness-dependent tumor cell growth." (PMID 40061015, 2025). "In tumor samples, more intense PIEZO1 expression was frequently noted in the peripheral part of the tumor." (PMID 40724850, 2025). "Functional studies identified Piezo1 as a key mediator, as its knockdown significantly impaired the tumor-suppressive effects." (PMID 39940798, 2025). "These contrasting roles likely arise from differences in cellular context, tumor microenvironment, and downstream effectors, necessitating tissue-specific therapeutic approaches targeting Piezo1." (PMID 41017814, 2025).
tumor (continued). "Recent progress in cancer biology has brought attention to mechanosensitive channels such as PIEZO1 as potential contributors to tumor progression." (PMID 40724850, 2025). "By sensing mechanical cues in the TME—such as increased tissue stiffness and compression— Piezo1 influences the proliferation and migration of tumor cells, thereby contributing to tumor progression." (PMID 40821847, 2025). "Collectively, these results provide compelling evidence that PIEZO1 acts as a facilitator of tumor progression in LIHC." (PMID 40977743, 2025). "Various pathways such as the mitotic cell cycle, focal adhesion, ECM, and tumor cell response to mechanical stimuli were altered after the knockdown of Piezo1." (PMID 40061015, 2025). "For instance, activation of Piezo1 can induce Ca2+ influx, enhancing dendritic cell (DC) activation and antigen presentation, which boosts the body’s anti-tumor immune response." (PMID 41195420, 2025). "PIEZO1 can augment CD8+ T cell exhaustion via activation of the transcription factor OSR2 in the tumor microenvironment." (PMID 40454475, 2025). "Knockdown of Piezo1 by shRNA or the Piezo1-specific antagonist GsMTx4 inhibited tumor growth in vitro and in vivo in DU145 cells and xenograft nude mouse models." (PMID 40507332, 2025). "The resulting mechanical tension initially activates Piezo1, which is highly expressed at both intracellular and extracellular domains, positioning it as a mechanical hub for tumor cell–ECM communication." (PMID 40821847, 2025). "Within the specifically isolated hepatocyte populations, malignant hepatocytes derived from tumor tissues exhibited a significantly higher average expression level of PIEZO1 compared to normal hepatocytes derived from adjacent normal tissues." (PMID 40977743, 2025). "Pharmacologic inhibition of Piezo1 (e.g., with GsMTx4) can partly restore T-cell infiltration and boost effector function, highlighting the bidirectional regulatory role of Piezo1 in T-cell–tumor cell crosstalk." (PMID 40821847, 2025). "Increases in matrix stiffness, stromal fibrosis, and abnormal hemodynamics can all be sensed and transduced by tumor cells via Piezo1 channels." (PMID 41195420, 2025). "Correlating with the smallest mean tumor volume, the mean Piezo1 expression was highest for the 0 and 4 h treatment intervals, which were 75.6% and 81.5%, respectively." (PMID 39976192, 2025). "Such heterogeneity underscores the need for tumor-type-specific Piezo1-targeted strategies, such as TGF-β inhibitors in HCC and Hippo activators in NSCLC." (PMID 41017814, 2025). "Tumor cells thus form a feedback loop between Piezo1-dependent mechanosensing and abnormal tissue mechanics that interact and exacerbate disease." (PMID 40061015, 2025). "In tumor cells, Piezo1 promotes proliferation, invasion, and metastasis by activating oncogenic signaling and contributes to an immunosuppressive TME through regulation of cancer-associated fibroblasts (CAFs) and extracellular matrix (ECM) remodeling." (PMID 40821847, 2025). "This expression pattern contrasts with findings in several other solid malignancies, where PIEZO1 expression is typically upregulated in tumor tissues relative to adjacent normal tissues." (PMID 40724850, 2025). "In the context of tumor biology, Piezo1 contributes to malignant phenotypes including tumor proliferation, metastasis, and therapy resistance by modulating the mechanical properties and adaptability of cancer cells." (PMID 40821847, 2025). "TUNEL assay with these lung tissues showed that PIEZO1 depletion increased tumor cell death in lung capillaries." (PMID 41390768, 2025). "In summary, Piezo1, as a mechanosensitive ion channel, has emerged as a cutting-edge focus in cancer research due to its pivotal roles in tumor initiation, progression, and immune regulation." (PMID 40821847, 2025).
tumor (continued). "Mechanical stimulation of tumor cells by CD8+ T/NK cells activates the mechanoreceptor PIEZO1 on their surface, mediating the remodeling of their intracellular cytoskeleton and thus modulating their cytotoxic functions." (PMID 39799341, 2025). "Like our observations in ccRCC, their study identified PIEZO1 as a potential prognostic biomarker and therapeutic target, highlighting its role in tumor progression." (PMID 40724850, 2025). "High PIEZO1 expression was correlated with higher tumor grade (p = 0.0147) and shorter OS (p = 0.0047)." (PMID 40724850, 2025). "In this study, siRNA-mediated Piezo1 knockdown in MSCs impaired their response to ES, reducing tumor-suppressive CM production." (PMID 39940798, 2025). "RNA-Seq analysis of the TCGA cohort revealed that PIEZO1 mRNA expression is significantly upregulated in ccRCC tumor tissues compared to adjacent normal tissues and is associated with poor overall survival, suggesting its potential as a prognostic marker." (PMID 40724850, 2025). "Functional assays show that Piezo1-shRNA markedly slows subcutaneous tumor growth in nude mice, suppresses scratch-wound migration, and reduces pulmonary metastatic foci, whereas Yoda1 restores YAP activation and cell motility." (PMID 40821847, 2025). "Future studies should elucidate tumor-specific mechanisms of Piezo1 and optimize its exploitation as an immunotherapeutic target." (PMID 40821847, 2025). "Deletion of PIEZO1 abolished these effects, supporting a role for PIEZO1-dependent mechanotransduction in driving both the tumour cell pro-adhesive phenotype and the endothelial response." (PMID 40890143, 2025). "A large body of literature shows that Piezo1 plays an important role in tumor migration, extravasation, and distant metastasis (Lin CY." (PMID 38690080, 2024). "When the mechanosensor Piezo1 in T cells is blocked, it enhances their traction and intensifies cytotoxicity against tumor cells." (PMID 39430235, 2024). "The mechanism of regulation of Piezo1 expression by the tumor microenvironment, especially the extracellular matrix and angiogenic process, can be further investigated by exploring the interaction of Piezo1 with the tumor microenvironment." (PMID 39539343, 2024). "Arginine‐rich peptides play a pivotal role in enhancing mechanical sensing and cellular uptake through the Piezo1/integrin β1 axis, thereby establishing a positive feedback loop that ultimately promotes tumor‐targeted delivery." (PMID 39258781, 2024). "Piezo1 interferes with the apoptosis of tumor cells by inducing Ca2+ influx and mediating mitochondrial dysfunction." (PMID 38690080, 2024). "YAP, function as the downstream signal of Piezo1, was activated by R11 peptides entering into the nucleus, collectively enhancing the mechanical sensing and uptake of tumor cells." (PMID 39258781, 2024). "Some studies have found that suppressing the Piezo1 channel inhibits the proliferation and growth of tumor cells." (PMID 38690080, 2024). "Alterations in Piezo1 expression have been observed in several tumors by regulating key cell cycle regulators and thus affecting tumor cell proliferation." (PMID 38690080, 2024). "It is demonstrated that the over‐activated Piezo1/integrin β1 (ITGB1) signaling axis significantly facilitates tumor‐targeted delivery of R11 peptides via macropinocytosis." (PMID 39258781, 2024). "Gene therapy is also being explored to suppress the expression of Piezo1 to stop tumor growth and metastasis." (PMID 38690080, 2024). "The angiogenic switch is regulated by both pro-angiogenic and anti-angiogenic factors, and Piezo1 promotes tumor angiogenesis by up-regulating pro-angiogenic factors and their upstream and downstream effectors." (PMID 38690080, 2024). "Elevated solid stress in the tumor microenvironment can trigger the nuclear translocation of the transcription factor RUNX2 via Piezo1 activation." (PMID 39430235, 2024).
tumor (continued). "It is noteworthy to mention that the upregulation of Piezo1 expression has been observed to promote tumor cell proliferation in various carcinoma types." (PMID 39328029, 2024). "Effective delivery of Piezo1 inhibitors to tumor regions in the brain and ensuring drug stability and efficacy remain challenges to be addressed in clinical translational research." (PMID 39539343, 2024). "Second, the regulation of Piezo1 expression by the mechanical environment and its mechanism of action in the tumor microenvironment are not fully understood." (PMID 39539343, 2024). "Some studies have found that inhibiting the activity or expression of the Piezo1 channel can inhibit the growth and metastasis of tumor cells and enhance their sensitivity to chemotherapy drugs or ultrasonic therapy." (PMID 38690080, 2024). "A large number of other tumor developments are underway or have been found to be connected to Piezo1, and Piezo1 has great potential as an anti-tumor target." (PMID 38690080, 2024). "Piezo1 channels are also involved in tumor ECM organization, angiogenesis, and cell migration associated with the tumor microenvironment." (PMID 39539343, 2024). "Multiple studies have provided ideas for activating Piezo1 through Yoda1 agonists and participating in tumor treatment." (PMID 38690080, 2024). "Our work suggested the involvement of the Piezo1/ITGB1 signaling axis in the tumor‐targeted delivery of R11 peptides." (PMID 39258781, 2024). "In summary, how to effectively regulate the expression or activity of Piezo1, inhibit tumor progression, and buy enough time for later treatment needs further study." (PMID 38690080, 2024). "This study presents a novel approach to enhance tumor‐targeted delivery through the Piezo1/integrin β1 signal axis, involving in the formation and development of membrane fusion." (PMID 39258781, 2024). "Specific small molecule compounds and drugs have been found to inhibit Piezo1’s activity, thereby inhibiting tumor growth and metastasis." (PMID 38690080, 2024). "Based on the molecular mechanism of Piezo1, it is possible to clinically consider blocking the mechanosensitivity of tumor cells by inhibiting the activity of Piezo1 channels, thereby slowing tumor progression." (PMID 39539343, 2024). "At present, research on the effect of Piezo1 on tumor progression mainly focuses on tumor proliferation, apoptosis and metastasis, while few studies have been done on angiogenesis and cancer stem cells." (PMID 38690080, 2024). "The study suggests that targeting the Piezo1/integrin β1 axis initiated a positive feedback loop to enhance tumor‐targeted delivery." (PMID 39258781, 2024). "The over‐activated Piezo1/integrin β1 signaling axis significantly facilitates tumor‐targeted delivery." (PMID 39258781, 2024). "Multiple studies have found that the Piezo1 channel can increase the migration and invasion ability of tumor cells, and correspondingly, inhibiting its activity can weaken this migration and invasion ability." (PMID 38690080, 2024). "Next, we will describe the specific mechanism by which Piezo1 regulates tumor characteristics in detail." (PMID 38690080, 2024). "The over‐activated Piezo1/integrin β1 signaling axis significantly facilitated tumor‐targeted delivery." (PMID 39258781, 2024). "As a result, further research and clinical trials are needed that will help verify the efficacy and safety of Piezo1 as a tumor treatment target, and provide additional options for developing new treatment strategies." (PMID 38690080, 2024). "Knowing the important role of the Piezo1 channel in tumor development, the researchers began exploring using the Piezo1 channel as a new target for tumor treatment." (PMID 38690080, 2024). "The research suggests that the Piezo1 channel plays an important regulatory role in tumor development." (PMID 38690080, 2024).
tumor (continued). "Piezo1 is abnormally expressed in a variety of tumor tissues, and it is related to the malignant degree of some tumors and the survival rate of patients." (PMID 38690080, 2024). "To investigate the involvement of PIEZO1 in GC development more deeply, we delved into the TCGA dataset and observed an upregulation of PIEZO1 in tumour tissues." (PMID 37983931, 2023). "Piezo1 knockdown markedly inhibited tumor formation by the CCSCs compared to that in the control groups." (PMID 37306789, 2023). "Diminishing PIEZO1 levels induces an anti‐tumour response and amplifies sensitivity to therapeutics like Cisplatin and 5‐fluorouracil (5‐FU)." (PMID 37983931, 2023). "Activation of Piezo1 in overcrowded epithelial tissues promotes live cell extrusion and death, which is a potential mechanism for the inhibition of tumor cell proliferation." (PMID 37366640, 2023). "Piezo1 and Piezo2 participate in aberrant mechanical loading-induced apoptosis in chondrocytes, type II pneumocytes, and tumor cells." (PMID 37420255, 2023). "Piezo1 overexpression has also been correlated with genes related to the tumor microenvironment, which are connected with extracellular matrix reorganization, cell adhesion, and angiogenesis." (PMID 36837670, 2023). "Further analysis of paired GC samples confirmed this finding, showing a distinct upregulation of PIEZO1 in tumour samples relative to their paired normal tissue (n = 27)." (PMID 37983931, 2023). "Here we aimed to investigate the role of Piezo1, a gene related to the mechanical environment of the tumor, in promoting the metastasis of OC." (PMID 35942515, 2022). "PIEZO1 is overexpressed in aggressive cancers at focal adhesions where it augments tissue stiffening and tumor cell proliferation." (PMID 35942524, 2022). "Taken together, Piezo1 can respond to various mechanical forces to facilitate tumor angiogenesis by activating the HIF-1α pathway and promoting MMPs expression." (PMID 36230880, 2022). "Piezo1 mediates the assembly of focal adhesion structures and cytoskeleton, which elevate cell contractile force and thus enhance the mobility of tumor cells." (PMID 36230880, 2022). "Piezo1 has been reported to inhibit tumor cell apoptosis and contribute to survival by promoting MAPK-mediated YAP phosphorylation and activating the YAP signaling pathway, suppressing caspase-3-dependent apoptosis in HCC cells." (PMID 36230880, 2022). "As such, doxycycline-mediated shRNA knockdown of Piezo1 suppresses tumor growth and prolongs the survival of mice." (PMID 36158191, 2022). "We found that PIEZO1 expression was changed in different pathological stages of a few tumor types, including KIRC (p = 0.0202), PAAD (p = 0.0063) and STAD (p = 0.0469)." (PMID 35747124, 2022). "Further studies have demonstrated that Piezo1 is involved in several cancer processes, including the proliferation of tumor cells and the onset of cell death in the tumor." (PMID 36615408, 2022). "Another field explored in terms of Piezo1 activity relates its role in cancer development and tumor progression." (PMID 35897650, 2022). "Collectively, these results indicate that Piezo1 plays an important role in opening the initial invasion barrier of tumor cells that increases tissue invasion and metastasis." (PMID 36230880, 2022). "Piezo1 has also been shown to enhance the growth of human glioblastoma stem cells and promote tumor development by activating integrin/FAK signaling." (PMID 36158191, 2022). "We also analyzed the relationship between the PIEZO1 expression level and tumor pathological staging by GEPIA2." (PMID 35747124, 2022). "They observed that the stiff mechanical environment induces Piezo1 mechanosensors to activate signaling pathways in favor of tumor aggression, accessed by increased tumor growth." (PMID 35897650, 2022). "In their work, they suggested a mechanism by which the tumor mechanical environment promotes the increased activation of Piezo1." (PMID 35897650, 2022).